SMAD3 (SMAD family member 3)
Diseases named in the same sentence as SMAD3 in open-access papers (continued):
Sharing a sentence is not in itself a finding about the gene and the disease.
tumor (continued). "Smad3 is one of the key proteins in TGF-β pathway, which is one of the most important pathways in cancer biology, the activation of this pathway can inhibit the proliferation of tumor cells and influence the transcription of over 500 genes." (PMID 28454099, 2017). "In contrast, depletion of NK cells from the tumour-bearing hosts with a neutralizing antibody restored rapid progression of the B16F10 tumour only in Smad3−/− mice but not in Smad3+/+ mice in vivo." (PMID 28262747, 2017). "Our results indicate that the markedly high tumor burden in Smad3 mutant mice results from aberrant Toll-like receptor (TLR) expression as well as Wnt signaling, and demonstrate functional regulation of TLR7 through Smad3." (PMID 27456065, 2016). "Thus, TGFβ, via Smad3, induces KLF17 expression, and KLF17 suppresses tumor growth, providing input to the cytostatic action of TGFβ." (PMID 27367735, 2016). "However it has been demonstrated extensively that autophagy mediates tumor survival by supplying nutrients to stressed cancer cells, and promotes cancer invasion through the TGF-β/Smad2/Smad3 signaling pathway." (PMID 25980495, 2015). "First, in addition to acting as a tumor suppressor protein by negatively regulating Wnt signaling, AXIN also plays a positive role in TGF-β signaling and regulates TGF-β signaling by acting as an adaptor for Smad3, one of the TGF-β effectors." (PMID 26161041, 2015). "Advanced human cancer cells that retain TGF-β/SMAD signaling but lack tumor suppressive responses can make use of the SMAD pathway to their advantages, and via SMAD3/SMAD4 stimulate pro-invasive and pro-metastatic target genes (for example, IL11, CTGF, CXCR4) and reprogram (EMT) phenotypes." (PMID 24756567, 2014). "Although deacetylation of α-tubulin by HDAC6 and subsequent Smad3 activation seems to be an important event in the induction of invadopodia production in hypoxia, other data link HDAC6 to tumor progression and cancer cell invasion through deacetylation of other cytoplasmic substrates." (PMID 23405166, 2013). "In order to investigate the role of T and B cells in inflammation and tumor development in this model, we compared DSS-induced disease in Smad3−/− and Smad3/Rag-DKO mice using two different DSS regimens (single cycle of 1.5% DSS for 7 days or 9 cycles of 1.5% DSS)." (PMID 24244446, 2013). "These included transcription factor EGR1 which is reported to have tumor suppressor properties, genes involved in lymphocyte activation and differentiation such as BCL6, CD4 and SMAD3 and genes TLR3 and TIRAP that are part of the toll-like receptor signaling pathway." (PMID 23072359, 2012). "Inhibition ofTGF-β or Smad3 has been shown to suppresses the growth and metastasis of AItumours in Nude mice (but not tumour incidence) and, as for GLI, Smad3 is expressedat considerably higher levels in DU145 cells compared to LNCaP cells." (PMID 21633508, 2011). "Consequently, targeting GRM8 and similar regulatory genes may represent a viable strategy for reactivating sensitivity to the tumor‐suppressive and pro‐senescent effects of the TGF‐β/Smad3 axis." (PMID 40083231, 2025). "This included hypermethylation of negative TMRs associated with tumour suppressor genes, such as TGFBR2 and SMAD3, as well as loss of methylation at negative TMRs for the oncogenes ERBB3 and SND1 and for PTPN13, which is described as having both oncogenic and tumour suppressor roles." (PMID 41036619, 2025). "The importance of Smad3 in monocytic development was first highlighted by the increased frequency of CD11b+Ly6Clo cells (with higher CD86 expression) and fewer CD11b+Ly6G+ granulocytic cells in tumor-free mice overexpressing Smad3 in myeloid cells (Lys2-Smad3-AAV9)." (PMID 41360769, 2025).
tumor (continued). "The specific regulatory mechanism of THBS4 in both normal and tumor tissues is not well understood, among which transforming growth factor β (TGF-β) signaling has been shown to be closely related, and it has been reported that SMAD3 is involved in the regulation of THBS4 by TGF-β." (PMID 40303998, 2025). "Importantly, we revealed tumor cell-intrinsic ATP6V0A1 as a novel immunosuppressive factor that promotes RABGEF1-dependent cholesterol absorption in CRC cells, consequently initiating paracrine TGF-β1/SMAD3 signaling to deactivate memory CD8+ T cells." (PMID 38971819, 2024). "Importantly, macrophage‐specific genetic deletion and systemic pharmacological inhibition of TGF‐β1/Smad3/Runx1 signaling effectively prevent MMT‐driven CAF and tumor formation in vitro and in vivo, representing a potential therapeutic target for clinical NSCLC." (PMID 37967345, 2024). "Smad3-KO mice inoculated with LLC cells showed a marked increase in the abundance of neutrophils in both the circulation and the TME as shown by immunostaining and flow cytometry, as well as substantially less tumor growth on day 15 compared to wild-type controls." (PMID 37002229, 2023). "Enhanced recruitment of Smad3-KO-BMDN over that of Smad3-WT-BMDN into the TME was demonstrated in an adoptive transfer experiment in which equal numbers of dye-labeled Smad3-WT and Smad3-KO-BMDN were injected into tumor-bearing mice, and the TME examined 24 h later." (PMID 37002229, 2023). "Given that SMAD3, a major transcription factor in TGF-β pathway, acts as a tumor suppressor and its functional disruption was positively associated with CRC progression and metastasis, this fusion might lead to SMAD3 dysfunction, consequently suppressing the function of TGF-β pathway." (PMID 36812239, 2023). "Growing evidence has shown that miR-133a is downregulated and plays tumor suppressor roles in cancer and that it can inhibit proliferation, migration, and invasion of HCC cells by targeting several genes such as IGF-1R, FSCN1, and FOSL2 through the TGF-β/Smad3 signaling pathway." (PMID 35432524, 2022). "Our finding that Smyca binds Smad3 but not Smad2 to elevate the expression of pro-tumor effectors of Smad not only is consistent with these previous studies but also suggests Smyca as one factor that contributes to the differential effects of Smad2 and Smad3 on tumor progression." (PMID 35794621, 2022). "Furthermore, we demonstrated that there was a significant advantage to selectively blocking the SMAD3 signaling pathway rather than inhibiting global TGFBR signaling to prevent tumor progression and metastasis." (PMID 35681731, 2022). "Furthermore, CAM xenograft assays show the significant benefit of selective inhibition of the SMAD3 signaling pathway as opposed to global TGFβ inhibition in preventing tumor progression." (PMID 35681731, 2022). "In addition, we demonstrated a significant advantage in selectively inhibiting the SMAD3 signaling pathway rather than inhibiting global TGFBR signaling to prevent tumor progression and metastasis." (PMID 35681731, 2022). "Mechanistically, a Smad3‐centric regulatory network is upregulated in the MMTs of NSCLC, where chromatin immunoprecipitation sequencing(ChIP‐seq) detects a significant enrichment of Smad3 binding on fibroblast differentiation genes in the macrophage‐lineage cells in LLC‐tumor." (PMID 34791825, 2022). "Indeed, EPCs in tumor-bearing mice have overactivated SMAD2 and SMAD3." (PMID 33669537, 2021). "However, based on our results, a reduction in Smad3 abundance may also remove a barrier to induction of EMT and invasive activities, mediating relief from the tumor-suppressive effects of aTGF-β1 and RAC1b." (PMID 33478130, 2021). "Therefore, to confirm our results, TGF-β/Smad3 signaling pathway was detected in primary and tumor cell lines transfected with or without Tipe2 plasmid." (PMID 34702807, 2021). "Unlike Smad2 and Smad4, Smad3 nuclear localization is diminished in tumor samples." (PMID 34501347, 2021).
tumor (continued). "GBM cells can undergo transitions in molecular subtype in response to chemotherapy or radiotherapy and according to the microenvironment of the tumor, which may lead to differences in effects between in vitro and in vivo experiments using HIF-1α and Smad3 inhibitors." (PMID 34707087, 2021). "Previous reports imply that several transcription factors, such as SMAD3/5, can bind to the promoter region of CD73;16 therefore, we hypothesised that TGF-β1 or BMP4, both of which are highly expressed in the tumour microenvironment, may function as a catalyst in this interaction." (PMID 32345959, 2020). "Consequently, TrkB could inhibit the TGF-β-mediated tumor suppressor activity through direct interactions with SMAD2, SMAD3, or SMAD4, as exemplified by c-Myc and Tax." (PMID 32340410, 2020). "Moreover, a number of oncomirs and tumor-suppressor miRNAs are differentially regulated by CSC (microarray analyses), which could contribute to Smad3 and BCL-2 regulations." (PMID 32668597, 2020). "However, a-CTLA-4 fails to counteract autocrine/paracrine TGFβ signaling, thereby resulting in NFAT/SMAD3-mediated upregulation of FOXP319 and a paradoxical increase in tumor-infiltrating Tregs in the TGFβ-enriched immune microenvironment found in the majority of cancers." (PMID 29467463, 2018). "Taken together, the preclinical study using in vivo mouse model confirms that targeting the newly identified ERβ/TGF‐β1/SMAD3 signals with the FDA‐approved anti‐estrogen ICI182,780 or the selective ERβ antagonist PHTPP could more effectively reduce RCC tumor growth and invasion." (PMID 30171816, 2018). "Since FOXP3-CNS1 region is crucial for TGFβ-mediated FOXP3 induction, we next asked the question whether in tumor-CD8+ Treg cells SMAD3 regulates CNS1 activity or not." (PMID 28487507, 2017). "Conversely, in the tumour stroma, several cells with spindle‐like morphology were triple‐positive for calretinin, α‐SMA, and nuclear pSmad3, confirming that MCs have activated TGF‐β–Smad3‐dependent signalling, undergone an MMT, invaded the stroma, and trans‐differentiated into CAFs." (PMID 28247413, 2017). "Mice lacking Smad3 are protected against tumour growth, invasion, metastasis and death." (PMID 28262747, 2017). "Similarly, by virtue of its involvement in Smad3/4 localization and subsequent activation of Smad3/4, β2SP may enhance TGF-β tumor suppressor function." (PMID 29234487, 2017). "For the first time, we demonstrate that the TGF-β1-(p-Smad3)-RBP2-E-cadherin-Smad3 feedback circuit may be a novel mechanism for EMT and GC metastasis and targeting RBP2 expression may have therapeutic advantage for the prevention of tumor metastasis." (PMID 25974964, 2015). "This TGF-β1-(p-Smad3)-RBP2- E-cadherin-Smad3 feedback circuit may be a novel mechanism for GC malignant progression and suppression of RBP2 expression may serve as a new strategy for the prevention of tumor distant metastasis." (PMID 25974964, 2015). "Furthermore, we found that the PCNA level was negatively correlated to the Smad3 level, suggesting that downregulation of Smad3 may contribute to the inactivation of TGF-β signaling and the promotion of tumor growth." (PMID 24636138, 2014). "Additionally, no invasive neoplasia was detected in Smad3+/− or WT mice at 17 weeks post DSS exposure." (PMID 24244446, 2013). "SMAD3 knockout mice, subjected to the two-stage chemical carcinogenesis protocol, showed a high resistance to the cancer development, indicating the importance of the intact SMAD3 signaling for the TPA-induced TGF-β overexpression during tumor promotion in the skin." (PMID 23984088, 2013). "Combination of treatments that inhibit stroma cell infiltration, cause apoptosis of myofibroblasts and inhibit Smad3 phosphorylation, with chemotherapy that increases tumor-cell apoptosis without affecting Smad3 phosphorylation was more efficacious than either treatment alone." (PMID 22848627, 2012).
tumor (continued). "Moreover, we demonstrate that different thresholds of Smad3 activation dictate the TGF-β responses in hepatic cells and that HCV core protein, by decreasing Smad3 activation, may switch TGF-β growth inhibitory effects to tumor promoting responses." (PMID 19190755, 2009). "Pharmacologic and macrophage-specific inhibition of Smad3 not only blocks MNT formation but also markedly alleviates spontaneous nocifensive behavior in tumor-bearing mice, suggesting that targeting MNT may serve as a dual-function strategy to suppress both tumor progression and cancer pain." (PMID 41009819, 2025). "Because we observed SMAD3 phosphorylation in stromal cells, we further extended our question to whether Inhba knockdown influences CAF activation states and subsequent T cell infiltration which would be an alternative pathway to hinder tumor growth and metastasis." (PMID 37083240, 2023). "While Smad3 signaling promotes a protumor N2 state in TANs, the lack of Smad3 in neutrophil results in the opposite outcome, with TANs polarization into an N1 state with a potent antitumor activity based on increased recruitment and increased tumor cytotoxicity." (PMID 37002229, 2023). "To conclude, our evidence may be limited though, but preliminarily microRNA-21 increases tumor burden and decrease tumor cell apoptosis in a MAPK-dependent manner and microRNA-145 suppresses tumor progression via domain-specific phosphorylation of Smad3 in HCC." (PMID 29156696, 2017). "Our previous study found that MUC1 gene silencing decreased Smad3 mRNA level in HCC cells, and another study has shown that MUC1 can active JNK to inhibit cell apoptosis, thus leading to the hypothesis that MUC1 shifts Smad3 from tumor-suppression to oncogenesis by activating JNK in HCC cells." (PMID 25714018, 2015). "Knocking-off experiments have showed that the TGF--induced SMAD3-mediated transcriptional response, was mitigated and enhanced by SMAD3 and SMAD2 knockdown, respectively, and this could be directly correlated with divergence in the regulation of tumor angiogenesis in vivo." (PMID 22952604, 2012). "However it is clear that Smad3 function in keratinocytes or other resident or infiltrating cells in the skin are critical for tumor promotion, further studies with epidermal specific deletion of Smad3 will provide insight as to the lack of SCC formation in Smad3−/− mice." (PMID 23326666, 2012). "Immunohistochemical analysis of 637 ccRCC tissue samples revealed a negative correlation between expression of SMAD3 and SMAD4, and the age of patients, nuclear grade, tumor size, as well as pTNM stage." (PMID 31842336, 2019). "Our data showed an increase in TGFβ level but decrease in Smad3 induced by MCT treatment, but it is still not clear if MCT plays a role in tumor through acting on TGFβ signaling pathway." (PMID 29420554, 2018). "The increase in mature NK1.1+ NKp46+ NK cells was also observed in the tumour, spleen and blood of the B16F10-rechallenged mice lacking Smad3." (PMID 28262747, 2017). "Noteworthy, no significant changes in TGF-βRI expression, in SMAD3 localization nor in vascularization, were observed in chemosensitive HCT116 xenograft tumor sections, suggesting that the observed molecular events are selective for chemoresistant tumors." (PMID 26956045, 2016). "Moreover, Linker phosphorylation of Smad3 indirectly inhibits Smad3 C-terminal phosphorylation and subsequently suppresses pSmad3C signaling, The TβRI/pSmad3C and JNK/pSmad3L signals oppose each other, and the balance could shift from tumor suppression to carcinogenesis." (PMID 27835881, 2016). "Using shRNA knockdown, we found that Smad3 but not Smad2 mediates the TGF-β-induced tumor suppressive responses in M3 tumors, and this tumor suppressive effect of Smad3 was lost in the more malignant M4 cell line." (PMID 24890385, 2014).
tumor (continued). "Thus, we identified, for the first time, that transcription factor Smad3 is specific to the differentiation of tumor MO-MDSC but not PMN-MDSC, whose reduction leads to accumulation of immature MO-MDSC during tumor progression." (PMID 41360769, 2025). "Indeed, m6A levels were higher in Smad3 transcripts from BM-MDSC and tumor MO-MDSC than in primary BMC, which showed no notable m6A modifications." (PMID 41360769, 2025). "In this sense, inhibition of the AP‐1, SMAD3 and RUNX1/RUNX2 pathways, in combination or not with the chemotherapeutic agent temozolomide, led to the subtype‐specific impairment of tumour growth, particularly in the context of the aggressive, mesenchymal‐like subtype." (PMID 37357610, 2023). "By analyzing the RNA‐seq data and through multiple fundamental experiments, we confirmed HOOK1 inhibited the TGF‐β/ALK5/p‐Smad3 canonical signaling pathway and the noncanonical TGF‐β/MEK/ERK/c‐Myc signal, which contributed to suppress the tumor growth and metastasis in ccRCC." (PMID 37085921, 2023). "Collectively, SMAD3 did not bind to the promoter of MET to induce the expression of SNAIL, but rather, it regulated SNAIL in a direct way, which indicated the complexity of tumor progression." (PMID 28837140, 2017). "The downstream activation of SMAD3 did not involve regulation of SMAD4, as expression levels of this protein did not change in any treatment nor in xenograft nor in 3D-cultured tumor cells." (PMID 26956045, 2016). "MUC1 acts as an oncogene to promote tumor formation and progression by regulating multiple proliferation-promoting signaling pathways; however, whether MUC1 mediates Smad3 signaling in cancer cells has not previously been reported." (PMID 25714018, 2015). "Consistent with our finding in LSMC, interaction of catalytic IKK subunits with Smad3 during TGFβ-SMAD-mediated EMT has been reported to occur independent of NF-κB activity, contributing to tumor-promoting function of TGFβ-SMAD signaling pathway and cellular invasion." (PMID 24755559, 2014). "Ectopic expression of the SMAD3 2KQ mutant, but not WT, not only rescued KAT6A KD‐inhibited tumor growth, lung metastasis, markedly reduced the animal survival, but also promoted MDSCs recruitment to lung tissues and primary tumor, CD4+/CD8+ T cells depletion in metastatic lung tissues." (PMID 34392614, 2021).